NOX1 (NADPH oxidase 1)
Diseases named in the same sentence as NOX1 in open-access papers (continued):
Sharing a sentence is not in itself a finding about the gene and the disease.
small intestinal tumors (1 paper, 2020). "In the present work, we have provided additional evidence that NOX1 is a relevant molecular target in gastrointestinal malignancies by demonstrating overexpression in clinical colorectal and small intestinal tumors at the protein level." (PMID 32428030, 2020). "Furthermore, we demonstrate by IHC that NOX1 staining intensity significantly differed between malignant colon and small intestinal tumors when compared to normal colonic and small intestinal mucosa." (PMID 32428030, 2020).
Smith-Lemli-Opitz syndrome (1 paper, 2014). Smith-Lemli-Opitz syndrome (SLOS) is characterized by multiple congenital anomalies, intellectual deficit, and behavioral problems. "Nox1 subunit of NADPH oxidase was also demonstrated to be of importance for UVA-induced ROS and PGE2 production, which might cause photosensitivity to UVA in patients with Smith-Lemli-Opitz syndrome (SLOS)." (PMID 24669283, 2014).
squamous cell carcinomas of the skin (1 paper, 2024). "Moreover, XPC knockdown in keratinocytes was associated with elevated levels of reactive oxygen species through altered AKT1 and NOX1 pathways, resulting in squamous cell carcinomas of the skin." (PMID 38672576, 2024).
transient cerebral ischemia (1 paper, 2015). "Moreover, inhibition of Nox1 in the peri-infarct region can improve neurological dysfunction and enhance the survival of new neurons in the peri-infarct region by inhibiting apoptosis and downregulation of superoxide generation after transient cerebral ischemia in rats." (PMID 25617620, 2015).
urolithiasis (1 paper, 2021). Stone(s) within the urinary tract. "On the other hand, our group reported that both MCP-1 and NFkB1 enhanced expression correlated to changes in oxidative stress levels and Nox1 upregulation in an ethylene glycol-induced rat model of urolithiasis." (PMID 34064366, 2021). "Moreover, our group recently reported higher levels of superoxide, mostly derived from NOX-1 in the kidney cortex and renal interlobar artery from an ethylene glycol-induced rat model of urolithiasis." (PMID 34064366, 2021).
α-synucleinopathies (1 paper, 2024). "Future studies to analyze in depth the effect of miR-124-3p in p47phox, p67phox and Rac1 activation will allow to discriminate the modulatory effect on the NOX1 signaling pathway and indirectly in α-synucleinopathy." (PMID 38451434, 2024). "This is the first study showing that miR-124-3p decreases PQ-induced α-synuclein levels and the associated NOX1/Rac1 signaling pathway, and impacts PITX3 protein levels, supporting the potential of miR-124-3p as a disease-modifying agent for PD and related α-synucleinopathies." (PMID 38451434, 2024).
tumor (113 papers, 2010 to 2026). "NOX1 has been implicated in a variety of pathological processes, including vascular dysfunction, tumor angiogenesis, and fibrotic disease." (PMID 40427384, 2025). "Tumor progression relies on membrane-associated NADPH oxidase 1 (NOX1) generating extracellular superoxide anions and H2O2, which are crucial for maintaining malignant cell growth." (PMID 38069213, 2023). "Pharmacological ADAM17 inhibition with TMI-5 resulted in additive inhibitory effects on tumor growth despite NOX1 deficiency in the mice." (PMID 38137406, 2023). "In vivo tumor growth and ex vivo tumor size analyses revealed that treatment with TMI-5 prevents MC38 tumor growth in WT mice as compared to IgG or vehicle-treated mice, as well as in NOX1-deficient mice as compared to WT mice." (PMID 38137406, 2023). "In parallel, MC38 tumor-bearing NOX1-deficient C57BL6/J mice were also treated with GKT771 or vehicle compound." (PMID 38137406, 2023). "Inactivation of membrane-associated catalase of tumor cells reactivates extracellular NOX1-driven ROS/RNS signaling through the NO/peroxynitrite or the HOCl signaling pathway." (PMID 34679719, 2021). "Membrane-associated catalase in cooperation with SOD protects the tumor cells (i) from intercellular HOCl signaling and (ii) from the aquaporin-mediated influx of NOX1/SOD-derived H2O2." (PMID 34679719, 2021). "Inducing syngenic LLC1 or B16 tumors, the authors showed that NOX1 deficient mice displayed less tumor vascularization and growth." (PMID 32785018, 2020). "Studies support that an increase in ROS generated from NOX1 activates the NF-κB signaling pathway which is associated with the early stages of tumor activity." (PMID 32856850, 2020). "A small, insignificant reduction of tumor lymphangiogenesis was observed in NOX1-deficient mice, suggesting the involvement of tumor-derived and NOX1-regulated factors." (PMID 31249132, 2019). "The potentiating effect of host NOX1 inhibition and anti–PD-1 antibody treatment on tumor growth was confirmed in NOX1-deficient mice treated with anti–PD-1 antibody." (PMID 31249132, 2019). "By contrast, the anti-VEGFR-2 antibody DC101 decreased tumor growth, and the effect was significantly stronger in NOX1-deficient mice than in WT mice." (PMID 31249132, 2019). "An additional in silico analysis was performed by matching the LKB1 mutational status and NOX1 mRNA transcript data of tumor cell lines, available at the COSMIC and Cancer Cell Line Encyclopedia web sites, respectively." (PMID 29915721, 2018). "Inhibition of NOX1 activity attenuated cytotoxic effects of oxidative stress in LKB1-deficient tumor cells in vitro and was an effective strategy to prevent the angiogenic switch and growth of LKB1-deficient A549 tumors in vivo." (PMID 29915721, 2018). "NOX1 accounted in part for enhanced cytotoxic effects of H2O2-induced oxidative stress in A549 LKB1-deficient tumor cells." (PMID 29915721, 2018). "We have also shown that inhibition of NOX1 activity with diphenylene Iodonium [DPI] or 2-di-thienyl Iodonium [DTI] also induced a G1 block in HT-29 cells with an associated decrease in tumor cell growth." (PMID 28498822, 2017). "The NOX1 subunit is over-expressed in several cancers and NOX1 derived ROS have been repeatedly linked with tumorigenesis and tumor progression although underlying pathways are ill defined." (PMID 25806803, 2015). "As NOX1 expression and the expression of membrane-associated catalase has been found to be a regular feature of tumor cells, photofrin-derived singlet oxygen should induce the same sequence of biochemical steps in tumor cells other than MKN-45 as well." (PMID 26225731, 2015). "To further analyze the link between NOX1 and PPARα in vivo, we injected LLC1 or B16F0 tumor cells in either WT or PPARα-deficient mice and treated these animals with the NOX1 inhibitor GKT136901." (PMID 21326871, 2011).
tumor (continued). "With respect to tumor growth, we observed differences between NOX1-deficient mice and wildtype mice treated with the NOX inhibitor." (PMID 21326871, 2011). "Furthermore, we found that high tumor NOX1 mRNA expression was associated with WT KRAS while both low ADAM17 and MCAM mRNA expression was associated with mutated KRAS." (PMID 38137406, 2023). "Bioinformatics analysis revealed a < 6% mutational frequency of NOX1 across pan-cancer tumor types." (PMID 37679792, 2023). "Loss of NOX1-dependent ROS production is associated with diminished tumor cell proliferative capacity that may be due, in part, to a block at the G1/S cell cycle interface." (PMID 34829628, 2021). "This regime, therefore, specifically addresses the biochemical interactions during novel approaches that target the distinct membrane-associated redox system of bona fide tumor cells, which are characterized by the expression of membrane-associated catalase and NOX1." (PMID 34679719, 2021). "NOX1 is implicated in colon cancer where its ROS-producing activity may enhance tumor cell proliferation and metastasis." (PMID 33312338, 2020). "Plasma VEGF-C was also decreased in NOX1-deficient versus WT MC38 tumor-bearing mice." (PMID 31249132, 2019). "However, several reports suggest that NOX1 is associated with tumor development and apoptosis in urothelial cancer." (PMID 29065504, 2017). "Inhibition of NOX1 expression in both 6A and G6 cells was associated with a substantial decrease in steady-state ROS levels when compared with the parental HT-29 line or tumor cells derived from the SC clone." (PMID 28330872, 2017). "Indeed, while plug- and tumor-induced angiogenesis was efficiently decreased in the NOX1-deficient mouse and by the NOX inhibitor, the latter was markedly more efficient in decreasing tumor growth." (PMID 21326871, 2011). "This differential expression of NOX1 may be associated with tumor occurrence and progression." (PMID 37679792, 2023). "In addition, NOX1 displayed low mutational frequency in 25 tumor tissues." (PMID 37679792, 2023). "Therefore, it may be concluded that mechanisms of tumor therapy that target membrane-associated catalase on NOX1-expressing tumor cells should require the cooperation of aquaporins with intercellular ROS/RNS-mediated signaling." (PMID 34679719, 2021). "However, the role of NOX1 in tumor-associated immune cells remains to be fully characterized." (PMID 31249132, 2019). "Accordingly, a NOX inhibitor or NOX1 down-regulation prevents adipocyte-enhanced ROS generation, Snail1 expression and tumor cell migration." (PMID 41943854, 2026). "Exosomes from tumor cells and their surrounding stromal cells act as messengers that transfer ROS-generating machinery (such as NOX1) and redox-sensitive molecules, thereby remodeling the microenvironment in favor of tumor survival and metastasis." (PMID 40427384, 2025). "The oxidation and inactivation of NRX by ROS that Nox1 produces alleviates this inhibition, augmenting β-catenin activity and facilitating tumor growth through the disruption of redox homeostasis." (PMID 40867215, 2025). "SHMT1 acts as a tumor suppressor in HCC by suppressing NADPH oxidase 1, thereby reducing ROS levels and inhibiting epithelial-mesenchymal transition." (PMID 40738465, 2025). "The Wnt/β-catenin pathway and oxidative stress are connected in glioblastoma: the Nox1 protein generates ROS, which amplifies β-catenin activity and drives tumor growth." (PMID 40867215, 2025). "The NOX1–ROS–exosome axis is now considered a critical mechanism for cross-talk between tumor cells and immune components, influencing not only redox balance but also TAM polarization, neutrophil behavior, and CD8+ T cell suppression." (PMID 40427384, 2025). "NOX1-derived ROS production has been shown to increase the formation and release of exosomes from tumor cells." (PMID 40427384, 2025).
tumor (continued). "In cancer, tumor cell-derived exosomes enriched with NOX1 have been shown to influence recipient immune cells, especially macrophages, by promoting M2 polarization and enhancing a pro-tumorigenic, immunosuppressive environment." (PMID 40427384, 2025). "NOX2, NOX4, and NOX5 mRNA levels increased with tumor progression stages, while NOX1 and DUOX1 expression decreased in more advanced stages." (PMID 38542437, 2024). "Some studies concerning NOX enzymes and BC have shown an upregulation of NOX1 in tumor tissues compared to normal tissues." (PMID 38542437, 2024). "NT5E (CD73), CSF ligands, CD274 (PDL1), IL1B, IL6, and IL10 transcripts were primarily found in the peri necrotic zone, whereas NOS2 (iNOS), TGFB2, and NOX1 expression is localized to cellular tumor regions." (PMID 39272914, 2024). "Based on these results, we propose that exosomal NOX1 promotes tumor growth and M2 macrophage infiltration by stimulating ROS production." (PMID 37679792, 2023). "In the present study, exosomal NOX1 promoted tumor growth and M2 macrophage infiltration in vivo by stimulating ROS production." (PMID 37679792, 2023). "In our experiments, suppression of NOX1 with a specific inhibitor reversed rhIL-17A-induced upregulation of tumor cell growth, ROS production, and stemness in AGS cells." (PMID 36125689, 2023). "The interplay between SOD/catalase and active NOX1 in tumor cells enables selective apoptosis induction when the protective system is disrupted, offering the potential for selective tumor cell apoptosis in vitro and in vivo." (PMID 38069213, 2023). "NADPH oxidase 1 (NOX1), located on the X chromosome, is reported to be involved in a variety of pathogenic mechanisms including vascular disease, tumor angiogenesis, and fibrosis." (PMID 37679792, 2023). "Expression of NOX1 in tumor and adjacent normal tissues for each tumor type was calculated using R language software and significant differences were analyzed." (PMID 37679792, 2023). "For example, oncogenic RAS increases superoxide production by upregulating NOX1 transcription through the MAPK pathway to promote tumor formation." (PMID 37649607, 2023). "Consistently, pharmacological NOX1 inhibition, or NOX1 gene deletion, results in a decreased mMCAM plasma level in tumor-bearing mice." (PMID 38137406, 2023). "To address this question, we performed mouse MC38 (ADAM17-positive CRC cells) tumor growth-inhibition studies with TMI-5 (Apratastat) in both WT and NOX1-deficient mice." (PMID 38137406, 2023). "Independently, we previously observed that either NOX1 or sMCAM pharmacological inhibition impaired tumor growth and angiogenesis." (PMID 38137406, 2023). "We found that targeting sMCAM recapitulates most of the anti-tumor effects mediated by NOX1 targeting and involves the effects of the immune tumor microenvironment (TME)." (PMID 38137406, 2023). "In this study, we believe that the generation of ROS by the OPN/NOX1 axis can maintain tumor cell survival and malignant progression." (PMID 35418176, 2022). "LINC00674 contributed to the malignant behaviors of tumor cells, possibly by activating the NADPH oxidase 1 (NOX1)/mTOR signaling pathway in HCC." (PMID 36118523, 2022). "As shown in the IHC staining images of OPN and NOX1 in human HCC tissue microarray, the levels of OPN were positively correlated with levels of NOX1 in 24 HCC tumor samples." (PMID 35418176, 2022). "The involvement of NOX1 in cell proliferation, tumor growth, cell motility, epithelial-mesenchymal transition (EMT) and matrix metalloproteinase-2 production has been shown in in vitro studies." (PMID 33485364, 2021). "While we did not observe a reduction in HCC lesions in this preventive setting, NOX1i reduced the induction of tumoral stemness markers indicating the involvement of NOX1 in tumor aggressiveness." (PMID 33485364, 2021).
tumor (continued). "It is obvious that this tight control of the concentration of H2O2 derived from NOX1-dependent superoxide anions protects the tumor cells, but at the same time poses a serious problem for their need to control their proliferation by extracellular H2O2." (PMID 34679719, 2021). "Generally speaking, increased generation of Nox1-derived ROS is functionally required for Ras transformation phenotypes, upregulation of vascular endothelial growth factor, tumor progression and tumor cell migration." (PMID 33451139, 2021). "At week 15, daily treatment with GKT771 was initiated to evaluate the effect of NOX1 inhibition on tumor development." (PMID 33485364, 2021). "To explore the clinical significance of NOX1, we performed IHC staining of NOX1 in CSCC TMA and demonstrated that NOX1 expression level was significantly elevated in CSCC tissues compared to adjacent non-tumor tissues." (PMID 33968728, 2021). "It is predictable that varying degrees of NOX1, catalase, aquaporin, xCT, glutathione synthase and glutathione peroxidase expression can be expected in different tumor cell lines." (PMID 34679719, 2021). "Using this novel immunological tool, we have identified specific cellular systems suitable for the study of NOX1 tumor biology." (PMID 32428030, 2020). "NOX1/NOX2 deficiency mice showed decreased ROS production in TAM and impaired M2 differentiation, leading to tumor growth inhibition." (PMID 32788720, 2020). "Tumor vascularization was inhibited in wildtype, but not in PPARα knockout animals, which confirmed the repression of PPARα through NOX1 as an important event in favor of enhanced tumor angiogenesis." (PMID 32785018, 2020). "As the expression of membrane-associated catalase of tumor cells is modulated by tumor cell-derived superoxide anions and H2O2, siRNA-mediated knockdown of NOX1 causes strong downmodulation of catalase expression." (PMID 31578342, 2019). "Taken together, these results suggest that host NOX1 contributes to tumor growth, angiogenesis, and lymphangiogenesis." (PMID 31249132, 2019). "NOX1-deficient mice showed reduced tumor angiogenesis, thereby validating the effects observed with pharmacological NOX1 inhibition but still supported tumor growth." (PMID 31249132, 2019). "When NOX1 of tumor cells was blocked by AEBSF, induction of bystander effect inducing potential was strongly reduced." (PMID 31558835, 2019). "Again, PAM seemed to trigger a strong autoamplificatory secondary singlet oxygen generation by the tumor cells, as seen by the strong inhibitory effect of the NOX1 inhibitor AEBSF." (PMID 31578342, 2019). "Up to 12.5% PAM, apoptosis was selectively induced in control tumor cells (siCo) and was completely dependent on NOX1-derived O2⋅− and 1O2, as it was inhibited by AEBSF and histidine." (PMID 31578342, 2019). "When tumor size reached approximately 50 mm3, mice were randomly assigned to five groups and treated by oral gavage with the NOX1-specific inhibitor GKT771, the broad-spectrum inhibitor GKT831, or the anti–VEGFR-2 blocking antibody DC101." (PMID 31249132, 2019). "Treatment with the previously available NOX1/NOX4 inhibitor GKT831 also suppressed B16-F10 tumor growth, whereas it had only a weak effect on MC38 tumors." (PMID 31249132, 2019). "The effect of the NOX inhibitor AEBSF points to the role of tumor cell-specific NOX1 in this process, conceivably through generation of secondary 1O2." (PMID 31558835, 2019). "NOX1 inhibition in tumor cells in vitro decreased the production of VEGF-A and PLGF, two important angiogenic factors associated with tumor growth and progression." (PMID 31249132, 2019). "The results showed that the concentrations of both factors were lower in NOX1 KO than in WT tumor mice." (PMID 31249132, 2019). "Mechanistically, SHMT1 acted as a tumor suppressor by targeting NOX1 and subsequently restrained ROS production, EMT and MMP2 expression in HCC cells." (PMID 30755243, 2019).